GH1 (growth hormone 1)
Diseases named in the same sentence as GH1 in open-access papers (continued):
Sharing a sentence is not in itself a finding about the gene and the disease.
Hearing impairment (2 papers, 2023 to 2024). A decreased magnitude of the sensory perception of sound. "The findings in our study may suggest a possible association between gH1 genotype and early infancy hearing loss." (PMID 37009289, 2023). "We found that among these infants with hearing impairment, 11 out of 13 ears from 8 newborns with moderate/severe hearing loss all exhibited the gH1 genotype rather than gH2." (PMID 37009289, 2023). "gH1 was the predominant genotype among symptomatic cCMV infected infants with moderate/severe hearing impairment although without statistical difference (p = 0.130)." (PMID 37009289, 2023).
triple-negative breast carcinoma (2 papers, 2015 to 2017). An invasive breast carcinoma which is negative for expression of estrogen receptor (ER), progesterone receptor (PR), and human epidermal growth factor receptor 2 (HER2).
fetal growth restriction (1 paper, 2005). A fetus that does not grow beyond the 10th percentile of conventionally accepted weight for gestational age. "Here, we use a stringently selected set of subjects to report suggestive association of SNPs in GH1 with fetal growth restriction." (PMID 15691369, 2005).
HCMV infection (1 paper, 2021). "Genotype-specific IgG responses to gB1, gB2/3, gB4, gH1, and gH2 were tested in 25 women with non-primary HCMV infection." (PMID 33802390, 2021).
latent infection (1 paper, 2023). "We observed in a previous study that the gH1 genotype was predominant in infants with active CMV infection, while gH2 was more prevalent in children with latent infection." (PMID 37009289, 2023).
multiple epiphyseal dysplasia (1 paper, 2023). Multiple epiphyseal dysplasias (MED/EDMs) are characterized by epiphyseal anomalies causing joint pain early in life, recurrent osteochondritis and early arthrosis. "Moreover, ES variable splicing causes GH1 third exon jumping resulting in a 17.5 kD GH isoform, which is an essential factor contributing to height defects in patients with autosomal dominant growth hormone deficiency (type II), and the gene may be associated with multiple epiphyseal dysplasias." (PMID 37174506, 2023).
tumor (186 papers, 1971 to 2026). "Scatter plot analysis revealed marked differences in GH1 gene expression levels among tumor cells within each sample, highlighting the ITH of hormone secretion across individual cells within the same tumor." (PMID 40852938, 2025). "PITX1 is considered a tumor suppressor gene, and is known to influence the expression of GH1, and is related to IGF-1." (PMID 40951278, 2025). "The authors of this article compared tumor and normal cells and found that in normal tissues, many cells coexpress GH1 and PRL, while most tumor cells only express one." (PMID 39114291, 2024). "The antiproliferative effects of metformin have been observed on an ACTH-secreting mouse corticotroph tumor cell line and growth hormone-secreting PitNET cell lines, GH3 and GH1." (PMID 39199391, 2024). "In depth analysis enabled us to separate the tumor clusters into GH1 and PRL expressing cells, the immune cells into CD4 T cells, CD8 T cells and monocytes (with subcategories, cf. Immune cell analysis) and structural cells into stem cells, pericytes, fibroblasts and endothelial cells." (PMID 40523964, 2025). "Interestingly, GH1 displayed opposite correlations depending on tumor stage and patient sex." (PMID 40806252, 2025). "We did not observe the relation between CNA status and other clinical/demographical features including patient’s age at surgery and sex, GH1 and IGF-1 in patients, as well as tumor size and invasive growth status." (PMID 39497133, 2024). "We also found that the cells expressing both GH1 and PRL had different expression patterns between the normal and tumor samples." (PMID 38167466, 2024). "The intratumoral heterogeneity was also explored using the Tumor Purity value, with which CXCL11, ERAP2, FYN, GH1, MAP3K14, and SEMA6C were found negatively correlated, while the rest were positively correlated." (PMID 36428747, 2022). "Although the protein expressions of PLAU, GDF11, EPS8 and GH1 in tumor and normal groups were not significantly different, the survival analysis results were consistent with our risk model results." (PMID 36741321, 2023). "Furthermore, we collected single‐cell data from four cases of GH‐secreting PitNETs from previous studies and found significant expression variability of the key growth hormone gene GH1 among individual cells, highlighting the heterogeneity of hormone secretion by tumor cells." (PMID 40852938, 2025).
cancer (178 papers, 2003 to 2026). A tumor composed of atypical neoplastic, often pleomorphic cells that invade other tissues. "Therefore, the increased expression levels of both Gh1 and Cst3 (as a positive co-expression) and cross talk between the factors, especially via responding to the estradiol pathway, may play a key role in the progression of cancer." (PMID 35180880, 2022). "Reports show that both leptin (LEP) and growth hormone 1 (GH1) could activate Janus kinase (JAK)–signal transducer and activator of transcription (STAT) cascade, which further induces angiogenesis, proliferation, and antiapoptotic pathways in normal cells and favors cancer progression." (PMID 32984004, 2020). "As for GH1, PRKCG, and PSPN, they are not known prognostic biomarkers, but GH1 is still regarded as strongly related to cancer development because of its key role in the stimulation of growth factor secretion (i.e., IGF-1)." (PMID 36428747, 2022).
endocrine disorder (71 papers, 2009 to 2026). "This represents the first report linking a homozygous GH1 promoter haplotype to IGHD, underscoring the role of noncoding variants in endocrine disease." (PMID 41561060, 2025).
infection (41 papers, 2005 to 2025). The state of being infected such as from the introduction of a foreign agent such as serum, vaccine, antigenic substance or organism. "GH1 genes are also expressed late in the infection of Arabidopsis by P. parasitica." (PMID 26332397, 2015). "Immunization with gH1-Qβ in the presence or absence of alum conferred significant protection against clinical symptoms of disease (p<0.05) and significantly reduced the weight loss associated with infection (p<0.05), as did Panvax." (PMID 24204639, 2013). "When comparing CAZy family level expression in cultured mycelium to infection stages, the most highly up‐regulated CAZy families were those that potentially act on plant polysaccharides such as cellulose (GH7, GH1, GH131), hemicellulose (GH12), starch (GH31), and pectins (GH43_6, GH78, PL3_2)." (PMID 34018655, 2021).
bacterial disease (2 papers, 2020 to 2023). "Six ZsBgl proteins belonged to GH1-h, which may induce systemic resistance to bacterial disease and pollen development." (PMID 37372316, 2023).
GH1 also shares sentences with these, for which no sentence is quoted: Insulin resistance (195 papers); diabetes (106); sarcopenia (88); Hyperglycemia (86); Turner syndrome (73); hypothyroidism (54); Hyperinsulinemia (43); Prader-Willi syndrome (41); hypogonadism (40); chronic kidney disease (39); malnutrition (33); metabolic syndrome (33); Hypertension (31); metabolic disorders (29); Anxiety (28); Noonan syndrome (26); cardiovascular disease (25); osteoporosis (25); deficiencies (24); hyperprolactinemia (24); prion disease (20); Creutzfeldt-Jakob disease (19); hypercortisolism (19); Alzheimer disease (18); anemia (18); Cachexia (18); Laron syndrome (18); Sepsis (17); atherosclerosis (16); Hepatic steatosis (16).
A further 636 diseases each share a sentence with GH1 in 16 papers or fewer.